LAMP3 (lysosome associated membrane protein 3)
Diseases named in the same sentence as LAMP3 in open-access papers (continued):
Sharing a sentence is not in itself a finding about the gene and the disease.
tumor (continued). "For instance, tumor/adjacent confined suppressive dendritic cells (i.e., DC subcluster 5) have been identified as a subset of dendritic cells (c21) with high expression of CD274, LAMP3, and CCL22, which may negatively regulate immune cells." (PMID 36333338, 2022). "Similarly to the results obtained by Iwamoto, we observed that the negative status of both ER and PR was related to LAMP3+ DC presence, which may contribute to tumour aggressiveness as well as resistance to tamoxifen therapy." (PMID 33919875, 2021). "Additionally, LAMP3+ DCs showed the highest level of CD274, which was even higher than what was observed in Tregs from BC tissues, indicating that this DC subgroup could inhibit CD8+ T cells directly or via recruiting Tregs into the tumor region." (PMID 33033240, 2020). "We found higher numbers of LAMP3+ DCs both intratumourally and at the invasive margin, as well as CD123+ DCs intratumourally in tumours with negative expression of oestrogen or progesterone receptors." (PMID 33919875, 2021). "The expression level of LAMP3 in ESCC was not significantly correlated with gender, tumor size, tumor location, histologic grade and pathologic stage, but was for age." (PMID 26263981, 2015). "Interestingly, our results demonstrated that LAMP3 expression was markedly related to tumour stage in HNSC, KIRC, KIRP, OV, PAAD and SKCM (all p < 0.05), but in other tumours, it did not correlate with the pathological stage (p > 0.05)." (PMID 38146591, 2024).
cancer (85 papers, 2011 to 2025). A tumor composed of atypical neoplastic, often pleomorphic cells that invade other tissues. "Then we analysed that LAMP3 copy number variations were significantly associated with immune infiltrates mainly in ten kinds of cancer, namely OV, PAAD, SKCM, UCEC, TCGT, HNSC, HNSC‐HPVneg, LUAD, LUSC and STAD." (PMID 38146591, 2024). "In conclusion, LAMP3 copy number variations and mutations have a sharp correlation with immune infiltrates in pan‐cancer." (PMID 38146591, 2024). "LAMP3 gene mutations in pan‐cancer were explored by the cBioPortal online tool, in which all TCGA Pan‐cancer data." (PMID 38146591, 2024). "High levels of LAMP3 are implicated in reduced progression-free survival and resistance to chemotherapy and radiation in several cancer types." (PMID 36572780, 2022). "PD-L1 is not only expressed in cancer cells but also on the surface of a variety of immune cells, especially in lysosomal associated membrane protein 3 (LAMP3)+ DCs." (PMID 36159866, 2022). "Secretory DCs bear a single-cell transcriptomic signature indicative of mature migratory LAMP3+ DCs associated with cancer and inflammation." (PMID 35418195, 2022). "CD63 (also known as lysosome-associated membrane glycoprotein, LAMP3), as the general tetraspanin protein, has been identified as the exosomal ‘star marker’ and overexpressed on the surface of exosomes from cancers." (PMID 36431072, 2022). "BTG2, IL7R, and LAMP3 are significantly downregulated in carcinoma samples, and their high expressions are markedly implicated with more prolonged overall survival, which is consistent with our study." (PMID 35372503, 2022). "In human primary breast epithelial cells, low dose BPA leads to hypermethylation and silencing of lysosomal associated membrane protein 3 (LAMP3) gene, whose overexpression is usually linked to cancer invasiveness." (PMID 32796699, 2020). "We demonstrate the significance of this approach by identifying several bacterial candidates and show that one of them (Prevotella bivia) upregulates a well-known human cancer driver, lysosomal associated membrane protein 3 (LAMP3)." (PMID 30294508, 2018). "With the evidence that LAMP3 is involved in hypoxia-induced cell migration, it needs to be elucidated which mechanism LAMP3 uses to cause the actual spread of cancer cells." (PMID 23294542, 2013). "They specifically suggested that Prevotella bivia(P. bivia) upregulate the human cancer driver lysosome-associated membrane protein 3 (LAMP3), which promotes metastasis and may help eliminate episomal HPV." (PMID 40612393, 2025). "Furthermore, we found that the expression of LAMP3 was sharply related to copy number variants and immune infiltration in pan‐cancer." (PMID 38146591, 2024). "We also showed that LAMP3 mutation could affect immune infiltration across multiple cancer types and immune cell types." (PMID 38146591, 2024). "Meanwhile, the major associations of LAMP3 with pan‐cancer existed in the immune‐associated processes of Antigen processing and presentation, Th17 cell differentiation, Th1 and Th2 cell differentiation, and the immune‐associated pathways of T cell receptor and B cell receptor signalling pathway." (PMID 38146591, 2024). "Taken together, these studies demonstrate that the presence of different DC subsets in the TME is correlated with cancer prognosis, with cDC1 and LAMP3+ DC mostly associated with a favorable prognosis while the role of other subsets such as pDC remains controversial." (PMID 39483484, 2024). "Furthermore, both immunoinhibitors and immunostimulators were sharply associated with LAMP3 in pan‐cancer expect KICH." (PMID 38146591, 2024). "Furthermore, pan-cancer analysis of single myeloid cells from human cancer types show that LAMP3+cDCs are associated with tumor progression, immune tolerance, and metastasis." (PMID 36291050, 2022).
cancer (continued). "In sum, while we cannot in effect rule out another gene within the region, the most likely candidate is Prkdc, since it carries a missense mutation on the causal allele shown before to confer cancer susceptibility, with Acvrf and Lamp3 arguably less likely candidates." (PMID 30681412, 2019). "The expression of LAMP3 was involved in the immune‐associated processes of Antigen processing and presentation, Th17 cell differentiation, Th1 and Th2 cell differentiation, and the immune‐associated pathways of T cell receptor and B cell receptor signalling pathways in most cancers." (PMID 38146591, 2024). "During their differentiation into LAMP3 + cDCs, their immunosuppressive functions are enhanced, providing valuable insights for the development of cancer immunotherapy strategies." (PMID 41214597, 2025). "Another pan-cancer scRNA-seq analysis demonstrated that LAMP3+ conventional dendritic cells (cDCs) are widely present, extending the conclusion of their diverse origins across all cancer types." (PMID 40857744, 2025). "The PERK/ATF4/LAMP3-arm mediates hypoxia-induced cancer cell migration, indicating that inhibiting this axis can result in the radiosensitization of BRCA cells." (PMID 41450825, 2025). "LAMP3+ DCs, as shown in recent cancer immunology studies, contribute to immune regulation by promoting CD8+ T cell exhaustion and recruiting regulatory T cells (Tregs), thereby establishing an immunosuppressive microenvironment." (PMID 40649852, 2025). "For example, LAMP3+ conventional DCs (cDCs) were observed to be widely present in different types of cancer, and greater abundance of TNF+ mast cells was found in NPC." (PMID 40954554, 2025). "Our results demonstrated that LAMP3 displayed a significantly positive relationship with nearly all TILs in various cancers except KICH." (PMID 38146591, 2024). "On the contrary, LAMP3 was almost irrelevant with all 6 types of cells in 4 out of 39 cancer types, namely ACC, DLBC, KICH and UVM." (PMID 38146591, 2024). "Elevated NSG2 levels both in cancer and stroma cells were linked to increased CD4+ T, CD8+ T, and Lamp3+ dendritic cells infiltration in stromal regions (P < 0.05)." (PMID 39493764, 2024). "BRCA and OV represent cancers in which patients with high LAMP3 expression had beneficial survival, while KIRC and PAAD represent cancers in which patients with high LAMP3 expression had unfavourable survival." (PMID 38146591, 2024). "Our study demonstrated that in most cancers LAMP3 expression was related to 6 kinds of immune cell infiltration, which was related to unfavourable prognosis and chemotherapy resistance." (PMID 38146591, 2024). "NSG2 expression positively correlated with CD4+ T cells, CD8+ T cells, and Lamp3+ dendritic cells in both cancer and stromal compartment, but negatively correlated with CD20+ B cells in stromal cells." (PMID 39493764, 2024). "High LAMP3 expression is correlated with unfavorable prognosis in patients with various cancers, including head and neck squamous cell carcinomas." (PMID 39429383, 2024). "Among chemokines, especially CCL4, CCL5, CCL8, CXCL9, CXCL10 and CXCL11 were markedly positive correlated with LAMP3 expression in most cancers." (PMID 38146591, 2024). "Our study analysed the expression of LAMP3 in pan‐cancer by various databases including TIMER, GTEx, TCGA, GEO, CCLE, HPA, TISIDB and so on." (PMID 38146591, 2024). "As a result, we concluded that LAMP3 predicts the prognoses of cancer patients and immune cell infiltration across cancers in the future." (PMID 38146591, 2024). "Another protein that predicted favorable outcomes by LIMMA was the LAMP3, a protein exclusively expressed on activated, mature DCs, and has been shown to predict good prognosis in other cancers (e.g., high-grade ovarian)." (PMID 38386171, 2024). "Although LAMP3 expression and its role have been studied in various cancers, limited studies have examined the relationship between LAMP3 and clinicopathological parameters in OSCC." (PMID 39429383, 2024).
cancer (continued). "Not only explored the expression and prognosis of LAMP3 in pan‐cancer, but also, we also explored the relationship between LAMP3 expression levels and TIME, such as expression of immunomodulators and immune cell infiltration." (PMID 38146591, 2024). "LUSC and LUAD represent cancers in which patients with low LAMP3 expression had beneficial survival." (PMID 38146591, 2024). "The prognostic value of activated or LAMP3+ DCs, features of mregDCs, have also been established for many cancer types." (PMID 39483484, 2024). "Subsequently, we analysed the predictive role of LAMP3 in patients with cancer who received immune therapies from the TIGER database." (PMID 38146591, 2024). "It is worth mentioning that the most relevant pathway for LAMP3 in pan‐cancer is NOD‐like receptor signalling pathway." (PMID 38146591, 2024). "Subsequently, the prognostic value of LAMP3 expression in pan‐cancer was assessed in online Kaplan–Meier Plotter web, whose data mostly come from TCGA." (PMID 38146591, 2024). "The immunohistochemistry was used to quantify the LAMP3 and PD‐L1 expression levels in cancer.High LAMP3 expression was found in most cancers and differentially expressed across molecular and immune subtypes." (PMID 38146591, 2024). "It has been demonstrated that ceRNA networks function critically in various human cancers, thus we attempted to predict and build the ceRNA network of LAMP3 exploiting many biological information databases." (PMID 38217544, 2024). "In conclusion, our study systematically analysed LAMP3 expression and its relevant signalling pathways, genetic alteration and relation to immune infiltration and immunomodulation in pan‐cancer." (PMID 38146591, 2024). "Subsequently, we analysed the role of LAMP3 in various cancers in GEPIA, whose data mostly come from RNA‐seq data from TCGA." (PMID 38146591, 2024). "Although we have a certain understanding of the relationship between LAMP3 and immunity, we still lack systematic study on the relationship between LAMP3 and immunity in pan‐cancer." (PMID 38146591, 2024). "Our data confirm the potential ability of LAMP3 in the prediction of immunotherapy response and indicate that LAMP3 is a promising biomarker for cancer immunotherapy." (PMID 38146591, 2024). "We also analysed the correlation between the LAMP3 expression and copy number from the TCGA database in pan‐cancer." (PMID 38146591, 2024). "Although the clinical implications of mregDC in cancers remain rudimentary, previous results emphasise the significant role that LAMP3, a typical marker of mregDC, plays in mediating better clinical outcomes of numerous solid cancers." (PMID 36808888, 2023). "Previous studies have demonstrated that LAMP3 affects the malignant behavior of many cancers (9-, 11)." (PMID 37878884, 2023). "Pan-cancer analysis has indicated an enrichment of LAMP3+ DCs and pDCs in tumors, with both normal tissues and tumors demonstrating a comparable abundance of cDC2s and cDC1s." (PMID 38012715, 2023). "The study also found that HAGLR, as a competitive endogenous RNA of miR‐143‐5p, increases the expression of LAMP3, thereby promoting the proliferation, invasion, and migration of cancer cells." (PMID 35028969, 2022). "In a pan-cancer analysis, researchers further found that cDC1-derived LAMP3+ DCs and cDC2-derived LAMP3+ DCs are under different ligand-receptor control, suggesting potentially diverse functions." (PMID 35646915, 2022). "There is some evidence that LAMP3 is required for cell survival during proteasomal inhibition and there have been some recent investigations into the role of LAMP3 in different cancers." (PMID 36016386, 2022). "Intriguingly, CCR7+LAMP3+ cDCs have been recently reported in cancer and have been characterized as mature DCs with a high potential for migration." (PMID 35618758, 2022). "Further investigation into LAMP3 expression in various stages of cancers is needed to determine the prognostic value of this protein." (PMID 36016386, 2022).
cancer (continued). "LAMP1, LAMP2, and LAMP3 are the key LAMP isoforms emerging as important potential players in cancer biology." (PMID 33430230, 2021). "In human cervix cancer, the hypoxic induction of PERK/eIF2α/ATF4 signalling up-regulates the pro-metastatic protein lysosomal-associated membrane protein 3 (LAMP3), linking hypoxic activation of PERK to another aggressive behavior of cancer cells." (PMID 33423689, 2021). "A pan-cancer single-cell immune atlas covering 15 cancer types verified the broad presence of LAMP3+ DCs, with variable abundance in different cancers." (PMID 34566965, 2021). "IHC staining showed that LAMP3 was detectable primarily in the cytoplasm of cancer cells and presented as brown particles, consistent with previous studies." (PMID 28607528, 2017). "The frequency of high LAMP3 protein expression in the cytoplasm of cancer cells was significantly higher in OSCC tissues than in the normal oral mucosa (P < 0.001)." (PMID 28607528, 2017). "For example, if a gene was down-regulated by LAMP3 siRNA, it is expected to be positively correlating to LAMP3 in the cancer gene expression data and vice versa (i.e. if gene is up after siRNA treatment correlation should be negative)." (PMID 27737689, 2016). "LAMP3 protein expression has been detected in both DC and epithelial cells in other types of cancer." (PMID 25362357, 2014). "While these findings were obtained in the context of cancer, they point to a potential immunomodulatory role for LAMP3+ DCs that may be relevant in autoimmune inflammation such as RA." (PMID 40649852, 2025). "Furthermore, we confirmed the unique features of the TME across cancer types by demonstrating that immunosuppressive myeloid cell types, specifically cDC_LAMP3 and pDC_LILR4, were also enriched in EC." (PMID 40785647, 2025). "From the previous results, LAMP3 genetic alterations were found in a variety of cancers." (PMID 38146591, 2024). "However, because of our detailed results, further investigations of the predictive role of LAMP3 in cancer immunotherapy need to be performed clinically and mechanically in individual cancer types." (PMID 38146591, 2024). "Similarly, LAMP3 showed a significantly positive relationship with nearly all MHC molecules in various cancers except KICH." (PMID 38146591, 2024). "Ccr7+Ido1+ DCs within the immunity hubs identified in our current study not only showed expression similarity with CCR7+LAMP3+IDO1+CD274+ activated DCs or mregDCs identified in human cancers, but also showed similar spatial co-localization with CD4+ and CD8+ T cells." (PMID 39414763, 2024). "Our study aims to provide a more systematic and comprehensive understanding of the role of LAMP3 in the progression of various cancers by various databases.We explored the role of LAMP3 in pan‐cancer using The Cancer Genome Atlas (TCGA) and Genotype‐Tissue Expression (GTEx) database." (PMID 38146591, 2024). "LAMP3 expression has been correlated with unfavorable prognosis in patients with various cancers." (PMID 39429383, 2024). "In this study, all poorly differentiated carcinomas showed high expression of LAMP3." (PMID 39429383, 2024). "The abundance of LAMP3+ DCs exhibits significant variability across different cancer types." (PMID 38012715, 2023). "LAMP3 has been confirmed to regulate migration and invasion in different cancers." (PMID 37878884, 2023). "In particular, the metastatic ecosystem was found to feature remarkable reprogramming of immunosuppressive cells such as FOXP3+ Treg cells, LAMP3+ tolerogenic DCs, CCL18+ M2‐like macrophages, RGS5+ cancer‐associated fibroblasts (CAFs), and LGALS1+ microglial cells." (PMID 36529697, 2023). "As a consequence, the predictive ability of CXCL10 and LAMP3 expression was sensible, illustrating the interplay between immunity and cancer, which could better reflect the therapeutic responsiveness in MIBC patients." (PMID 37082269, 2023).